EGFR (epidermal growth factor receptor)
Diseases named in the same sentence as EGFR in open-access papers (continued):
Sharing a sentence is not in itself a finding about the gene and the disease.
colorectal cancer (continued). "Phase three clinical trial evidence suggests that colorectal cancers with the KRAS G13D mutation may benefit from EGFR inhibitors, like cetuximab, in contrast to the other most common KRAS mutations." (PMID 33153459, 2020). "Similarly, EGFR is also highly expressed in colorectal cancer and is associated with the invasion and metastasis of colorectal cancer." (PMID 32148496, 2020). "Colorectal cancer (CRC) patients with Kristen rat sarcoma viral gene (KRAS) mutant tumors are associated with lack of response to anti-epidermal growth factor receptor (anti-EGFR) antibody therapy." (PMID 33226505, 2020). "Mutations in the Kirsten Ras (KRAS) oncogene occur in 30–40% of colorectal cancers (CRCs) and have been associated with poor prognosis and resistance to anti-epidermal growth factor receptor (EGFR)-targeted cancer therapy such as the monoclonal antibody panitumumab." (PMID 32300895, 2020). "EGFR is linked to colorectal carcinoma progression, and so is a widely used prognostic factor." (PMID 32170146, 2020). "The level of EGFR expression and the presence of mutations in signaling molecules downstream of the EGFR pathway have been reported to be determining factors for cetuximab responsiveness in patients with colorectal cancer; however, limited data have been reported for patients with HNSCC." (PMID 31014014, 2019). "In addition, PIK3CA mutations are significantly associated with resistance to the anti-EGFR treatments panitumumab and cetuximab, as well as progression free survival in colorectal cancer patients." (PMID 31769426, 2019). "Moreover, excessive activation of EGFR-ERK signaling has been implicated in human colorectal cancers (CRCs) and regimens containing anti-EGFR antibodies have been suggested as initial therapy in non-operable CRCs without KRAS mutation." (PMID 30974867, 2019). "EGFR has been recognised as a key pathogenic surface receptor in colorectal cancer for many years." (PMID 29254887, 2018). "Because RAS mutations are assessed in the routine diagnosis of colorectal carcinoma to assign epidermal growth factor receptor (EGFR) blockade therapy, we selected cells that are either wild-type for KRAS (HT-29), or carry the G12D and G13D mutations (LS174T and LoVo, respectively)." (PMID 29941002, 2018). "In addition, a clinically important novel finding of this study was that miR-193a-3p expression status was associated with the clinical outcome of colorectal cancer patients treated with anti-EGFR therapy." (PMID 29115941, 2017). "Interestingly, samples in which only EGFR variant 3 was overexpressed with genomic amplification were abundant in colorectal cancer samples." (PMID 28377632, 2017). "In addition, all our RAS-WT and BRAF-WT colorectal cancer patients were anti-EGFR resistant, a setting associated with MAPK pathway activation." (PMID 29108355, 2017). "Colorectal cancers less commonly harbour EGFR gene mutations." (PMID 28513565, 2017). "The differential sensitivity to BRAF inhibition displayed by BRAF-mutated melanoma and colorectal cancers may be partly explained by the EGFR protein." (PMID 29312543, 2017). "Since our results showed that miR-193a-3p was identified as a mutant-BRAF-specific miRNA, the worse outcome of colorectal cancer patients with the down-regulation of miR-193a-3p from anti-EGFR therapy may be confounded by the BRAF-mutation status." (PMID 29115941, 2017). "As proof of concept, we chose to investigate whether this approach could identify all clinically demonstrated resistance mutations in colorectal cancer patients treated with the EGFR monoclonal antibody Cetuximab." (PMID 28179366, 2017). "Association of RHBDL4/Rhbdd1 expression with colorectal cancer growth suggests that at least under pathogenic conditions this mechanism may promote EGFR signaling." (PMID 27264103, 2016).
colorectal cancer (continued). "However, immunohistochemical assessment of EGFR expression has not been a good predictor of response to the EGFR antibodies cetuximab or panitumumab in colorectal cancer, compared with EGFR copy number and KRAS mutation analysis." (PMID 27070783, 2016). "Activating mutations in KRAS are common in colorectal cancer but have also been reported in 5–16% of gastric and esophageal adenocarcinomas, causing unregulated signalling along its pathway, independently of EGFR status." (PMID 26844548, 2016). "The level of EGFR expression and/or the presence of mutations in signalling molecules downstream of the EGFR pathway have been reported to be determining factors for cetuximab responsiveness in colorectal cancer patients; however, limited data have been reported for HNSCC patients." (PMID 27399917, 2016). "Considering that KRAS mutations may also confer resistance to EGFR inhibitors, patients who have colorectal cancer with KRAS mutation could receive more tailored management." (PMID 27120810, 2016). "We find that clonal evolution during the acquisition of resistance impacts the clinical response to anti-EGFR therapy in colorectal cancer, and this may be influenced by the subclonal mutational landscape and environmental pressure on the tumour." (PMID 27929064, 2016). "Finally, the positive correlation of RHBDD1 expression with the EGFR/Raf/MEK/ERK signalling pathway is further corroborated in a murine model of colitis-associated colorectal cancer." (PMID 26300397, 2015). "Moreover, further studies demonstrated that for KRAS-mutated tumors (∼40% of colorectal cancer), anti-EGFR antibodies cause harm and decrease survival." (PMID 26320181, 2015). "However, an EGFR mutation S492R in colorectal cancer leads to resistance to cetuximab, which can be overcome by the newer EGFR antibody panitumumab." (PMID 26370727, 2015). "Instead of contradicting the importance of KRAS variability in the treatment of NSCLC, the different prognostic values of KRAS mutations in colorectal cancer versus NSCLC only confirm the need to determine how non-EGFR genetic variations affect the outcome of cetuximab treatment." (PMID 25962919, 2015). "Because EGFR is known to enhance MMP-7 expression in colorectal cancer, we verified whether EGFR was associated with MMP-7, YAP and MRLC on stiffer substrates." (PMID 26344692, 2015). "Similarly, colorectal cancer patients with low abundance of KRAS mutation have been reported to benefit from EGFR antibody therapy." (PMID 24398248, 2014). "In several studies, KRAS mutations in patients with colorectal cancer are associated with resistance to therapy with anti-EGFR antibodies and it is the only biomarker for predicting patient outcome when treated with targeted anti-HER therapies in colorectal cancer." (PMID 24609222, 2014). "Previous studies suggest that KRAS codon 61 and 146 mutations may also predict resistance to anti-EGFR therapy in colorectal cancer." (PMID 24885062, 2014). "As depicted above, it becomes also clear that combined approaches, like the inhibition of the EGFR/BRAF-axis in BRAF V600E mutated colorectal cancers, could be used to overcome primary resistance in histological subtypes." (PMID 24879454, 2014). "In summary, our findings suggest that EGFR mutation may underlie at least some cases of cetuximab responsiveness in colorectal carcinoma." (PMID 24894453, 2014). "A better understanding of the mechanisms underlying changes in KRAS in response to epidermal growth factor receptor (EGFR) inhibitors might contribute to improvement in the treatment of colorectal cancer (CRC)." (PMID 24304820, 2013). "In summary, our study showed that PNA-PCR method could easily detect the percentage of KRAS mutation in tumor cells and colorectal cancer patients with low abundance of KRAS mutation might benefit from EGFR antibody therapy." (PMID 23874486, 2013).
colorectal cancer (continued). "Colorectal cancer patients with low abundance of KRAS mutation might benefit from EGFR antibody therapy and further research is needed on a larger number patients." (PMID 23874486, 2013). "require KRAS mutational analysis on colorectal cancer prior to anti-EGFR therapy." (PMID 23536897, 2013). "Interestingly, BRAF mutations, which are predominantly mutually exclusive of mutant KRAS, have also been associated with resistance to anti-EGFR treatment in colorectal cancer." (PMID 23202889, 2012). "Although in colorectal cancer K-RAS mutations are the most useful biomarker for selecting patients who are candidate for treatment with anti-EGFR monoclonal antibodies, cetuximab or panitumumab, its role in NSCLC as prognostic or predictive marker is less defined." (PMID 27398239, 2012). "Overexpression of EGFR is found in more than 1/3 of the epithelial carcinomas and may be linked to an advanced stage or may predict a potential metastatic risk in the colon, indicating the importance of EGFR signaling in colorectal cancer development." (PMID 20828404, 2010). "Although the response to anti-EGFR mAbs observed in some patients has confirmed that EGFR activation is oncogenic, as predicted by cellular and animal models, the molecular mechanisms underlying EGFR activation in colorectal cancer remain obscure and are probably heterogeneous." (PMID 21139621, 2010). "Biomarker analysis of cetuximab in colorectal cancer has identified potential biomarkers such as EGFR gene amplification and K-ras mutations that may guide treatment decisions." (PMID 19127259, 2009). "Similarly, the KRAS G12C inhibitors sotorasib and JDQ443 had also displayed inhibitory effects on HRAS G12C and NRAS C12C, with the combination therapy of sotorasib and EGFR antibody panitumumab being successfully used to treat a patient with colorectal cancer with NRAS p.G12C mutation." (PMID 40304209, 2025). "Additionally, helical domain mutations are often associated with early-stage colorectal cancers, but they have also been linked to tumor resistance to certain therapies, such as anti-EGFR monoclonal antibodies, due to the persistent activation of downstream signaling pathways." (PMID 39555098, 2024). "Similarly, the presence of activating mutations in the genes encoding for the downstream effectors of EGFR could explain an intrinsic resistance to cetuximab, as is already known in colorectal cancer." (PMID 37298116, 2023). "However, it might also be due to racial difference as a previous Korean study reported EGFR mutation rate of 22.41% in 58 colorectal cancer patients." (PMID 37260182, 2023). "It has been reported that colorectal cancer patients with a mutation allele frequency (MAF)/variant allele frequency (VAF) of 0.1~5% in KRAS mutation in tumor tissue might benefit from the addition of anti-EGFR (cetuximab) to FOLFIRI chemotherapy." (PMID 37511664, 2023). "Because EGFR overexpression is found in 25 to 82% of colorectal cancer cells, cetuximab-modified nanoparticle carriers could be used as targeting moieties for detecting colorectal cancer cells with EGFR overexpression, as well as for other diagnostic and therapeutic purposes." (PMID 35455247, 2022). "However, somatic mutations of EGFR occur at a very low frequency in colorectal cancer." (PMID 36209184, 2022). "HER2 is a member of the epidermal growth factor receptor (EGFR) family with tyrosine kinase catalytic activity and is implicated in a variety of cancers with epithelial origin such as bladder, breast, ovarian, cervical, uterine, prostate, lung, kidney and colorectal cancer." (PMID 36230782, 2022). "Interestingly, the activity of vitamin C against KRAS/BRAF mutated colorectal cancer might be useful to counteract tumor resistance to anti-epidermal growth factor receptor (EGFR) monoclonal antibodies (i.e., cetuximab, panitumumab)." (PMID 33804775, 2021).
colorectal cancer (continued). "Interestingly, it was also shown in colorectal cancer that lower EGFR expression could be associated with better efficacy of anti-EGFR therapy." (PMID 31514305, 2019). "Likewise, the detection of KRAS gene mutations in ctDNA of colorectal cancer patients may indicate resistance to epidermal growth factor receptor inhibitors." (PMID 30364656, 2018). "One recent study has reported identification of four biomarkers in colorectal cancer tissue from 280 patients: carcinoembryonic antigen expressed in colorectal cancer 98.8% more than in normal tissue, tumor-associated glycoprotein-72 at 79%, folate receptor-α at 37.1%, and EGFR at 32.8%." (PMID 28911246, 2017). "Furthermore, activating mutations in KRAS or BRAF occur in approximately 50%–60% of patients with colorectal cancer; these mutations are mutually exclusive and are associated with resistance or decreased response to anti-epidermal growth factor receptor therapy in colorectal cancer." (PMID 28152546, 2017). "However, the effects of simultaneously targeting on VEGF and EGFR on the growth and angiogenesis of colorectal cancer (CRC), and its underlying mechanisms remain unknown." (PMID 27729020, 2016). "Furthermore, EGFR protein is over-expressed in many cancers even without evidence of focused genomic alteration, as observed in many cases of colorectal carcinoma where EGFR kinase domain mutations were found in only 3 out of 224 cases, 1.3% subjected to whole exome sequencing." (PMID 24894453, 2014). "We here show that such mutated colorectal cancer cells are highly sensitive to lysis by an EpCAM-specific T cell-engaging antibody, suggesting that redirected lysis by T cells is not affected by mutations in intracellular signaling proteins of the EGFR pathway." (PMID 20976159, 2010). "KRAS mutations in colorectal cancer primary tumors predict resistance to anti-Epidermal Growth Factor Receptor (EGFR) monoclonal antibody therapy in patients with metastatic colorectal cancer, and thus represent a true indicator of EGFR pathway activation status." (PMID 20020061, 2009). "By combining selective cytotoxicity with the potential to label cancer tissue using an imaging probe, EGFR-targeted immunoliposomes represent an integrated approach for more effective, safer, and personalized theranostic treatment of colorectal cancer." (PMID 41531750, 2026). "Among them, sorting nexin 1 (SNX1) was first identified as a protein interacting with the epidermal growth factor receptor (EGFR) and has since been reported to act as a tumor suppressor in various cancers, including lung, gastric, and colorectal cancers." (PMID 41487280, 2026). "Combining KRAS G12D and EGFR inhibition has demonstrated improved treatment efficacy, highlighting the potential of dual-targeting approaches in colorectal cancer therapy." (PMID 41604371, 2026). "Colorectal cancer (CRC) remains a major cause of cancer-related deaths in advanced disease, and activating KRAS/NRAS mutations limit the use of anti-EGFR antibodies to RAS-wild-type tumors." (PMID 41683587, 2026). "Our findings suggest that EGFR-tEVs + Dox represents a balanced therapeutic strategy that improves antitumor efficacy with a favorable safety profile for EGFR-positive colorectal cancer." (PMID 42074332, 2026). "Colorectal cancer (CRC), characterized by epidermal growth factor receptor (EGFR) overexpression, is often associated with poor prognosis and limited therapeutic response to conventional chemotherapy." (PMID 42074332, 2026). "Combining anti-EGFR antibodies with BRAF/MEK/ERK pathway blockade opened new treatment options for BRAFV600E-driven colorectal cancer." (PMID 41566838, 2026). "In colorectal cancer, the epidermal growth factor receptor (EGFR) has been widely explored as a therapeutic target, given its high expression in tumors, especially the most aggressive and metastatic ones." (PMID 41531750, 2026).
colorectal cancer (continued). "Molecular therapies targeting the EGFR/MAPK pathway have improved outcomes in colorectal cancer (CRC), yet acquired resistance remains a major clinical challenge." (PMID 42156502, 2026). "Approximately 30–40% of colorectal cancer cases harbor KRAS mutations, which are associated with a poor prognosis and resistance to certain treatments, including anti-EGFR monoclonal antibodies (panitumumab and cetuximab)." (PMID 39941797, 2025). "MET amplifications have been shown to contribute to anti-EGFR resistance in colorectal cancer, and de novo amplifications are one of the major mechanisms of acquired resistance." (PMID 41590338, 2025). "Among these, EGFR – the protein product of the HER-1 proto-oncogene – is a key oncogene in colorectal cancer whose receptor tyrosine kinase activity triggers essential signaling pathways for tumor cell growth and survival." (PMID 40919165, 2025). "While dual KRAS and epidermal growth factor receptor (EGFR) inhibition shows promise in treating KRAS-mutant colorectal cancer (CRC), resistance remains a major challenge." (PMID 41237766, 2025). "KRAS wild-type colorectal tumors are usually sensitive to EGFR blockade, e.g., cetuximab and panitumumab are one of the mainstays of targeted therapy for colorectal cancer, but resistance almost always develops within a few months of initiating therapy." (PMID 40438683, 2025). "Our SIRPα mAbs competed with CD47 for binding to human SIRPα and exhibited a potent phagocytic effect when combined with the anti-EGFR antibody on colorectal cancer cell lines." (PMID 40136470, 2025). "TGF-B secretion by stromal cells enhances metastatic capacity in colorectal cancer, while in PDAC, it induces a myofibroblastic phenotype of cancer-associated fibroblasts via EGFR/ERBB2 signalling, promoting metastasis." (PMID 40826447, 2025). "Anti-epidermal growth factor receptor (EGFR) antibodies are now frequently used as one of the standard therapies for colorectal cancer." (PMID 40546348, 2025). "The results showed that BODIPY-Pep12 conjugates bind to EGFR more effectively than other conjugates, showing it to be a promising contrast agent for the detection of colorectal cancer and other EGFR-overexpressing cancers." (PMID 40906195, 2025). "Clinically, EGFR overexpression is observed in ∼60% to 80% of colorectal cancers, with a tendency toward higher prevalence in left-sided and metastatic lesions." (PMID 41346398, 2025). "Panitumumab, a monoclonal antibody targeting EGFR, is utilized in the treatment of colorectal cancer." (PMID 39995410, 2025). "In colorectal cancer, BRAF mutations also predict failure of the epidermal growth factor receptor inhibitors cetuximab and panitumumab and are associated with shorter overall and progression-free survival." (PMID 41440935, 2025). "It is well known that the overexpression of epidermal growth factor (EGFR) and its related pathways are the key regulatory factors of colorectal cancer." (PMID 39995410, 2025). "Given these intriguing recent reports, we conducted a systematic and comprehensive study to investigate the role of circ-EGFR in mediating sensitivity to cetuximab in colorectal cancer across various cell cultures and animal models." (PMID 41214390, 2025). "Despite the encouraging initial efficacy of KRAS G12C inhibitors, rapid drug resistance inevitably occurs, and EGFR signaling reactivation is one of the main resistance mechanisms to KRAS G12C inhibitors in patients with colorectal cancer." (PMID 40304209, 2025). "The epidermal growth factor receptor (EGFR) is overexpressed in a variety of solid tumors such as lung and colorectal cancer." (PMID 41289384, 2025). "KEGG analysis highlighted pathways such as gastric cancer, EGFR-tyrosine kinase inhibitor resistance, and colorectal cancer." (PMID 41141624, 2025).